LINC02848 (long independently transcribed non-coding RNA 2848)
Gene: Long non-coding RNA gene on chromosome 7 (63,899,881 to 63,951,510, forward strand). Ensembl gene ENSG00000226581.
Diseases named in the same sentence as LINC02848 in open-access papers:
LINC02848 is named in the same sentence as 1 disease in open-access papers, as found by Europe PMC text mining. Sharing a sentence is not in itself a finding about the gene and the disease. The quoted sentences say what the papers report.
viral meningitis (1 paper, 2024). Inflammation of the membranes surrounding the brain and spinal cord due to a viral infection. "In viral meningitis specific co-expression networks, a total of 9 significantly upregulated lncRNAs (AC243830.1, AC092111.1, CEROX1, AC246817.2, FAM66C, LINC01535, LINC02848, CHKB-DT, and C18orf15) were identified." (PMID 38347610, 2024).